ERBB2 (erb-b2 receptor tyrosine kinase 2)
Diseases named in the same sentence as ERBB2 in open-access papers (continued):
Sharing a sentence is not in itself a finding about the gene and the disease.
breast tumors (2,366 papers, 1995 to 2026). "who performed pathway analysis of transcripts that were differentially expressed in the different morphological structures of breast tumours and found that tumours arranged in small nests showed a more considerable association with the ERBB2 pathway." (PMID 40243160, 2025). "Restricting glucose availability reduced the proliferation of both Cpt1a-proficient and -deficient ErbB2+ breast tumor cells in a concentration-dependent manner." (PMID 39097623, 2024). "Six matched tumors (four initial breast tumors and two metastatic samples) were available in patients with an ERBB2 mutation identified in plasma." (PMID 38287892, 2024). "Next, we exploited an in vivo murine model using breast tumor cells lines derived from MMTV-NeuNT mice in which a mutated constitutively active form of rat ERBB2 (NeuNT) is expressed under the control of the mouse mammary tumor virus (MMTV)." (PMID 37176074, 2023). "About 20–30% of metastatic breast tumours overexpress the human epidermal growth factor receptor 2 (HER2/erbB2), which is associated with a poor prognosis." (PMID 37569598, 2023). "Overexpression and/or amplification of HER2/ERBB2/NEU have been shown to be a causal factor for breast tumor malignancy and poor prognosis of patients." (PMID 36581908, 2022). "Amplification of ERBB2 (HER2) is associated with clinically aggressive breast tumors, shorter disease/recurrence-free survival, and poor overall survival." (PMID 35392236, 2022). "Biomarker-led clinical trials of adjuvant HER2-targeted therapy to treat breast tumors with activating ERBB2 mutations are warranted in HER2− primary ILC." (PMID 32782013, 2020). "In HER2-positive breast tumors, the oncogene ERBB2 was shown to be susceptible to a mechanism called palindromic gene amplification, in which genomic segments undergo inverted or palindromic duplication." (PMID 33298903, 2020). "Human epidermal growth factor receptor HER3 (ErbB3), especially in association with its relative HER2 (ErbB2), is known as a key oncogene in breast tumour biology." (PMID 30367623, 2018). "Forty percent of ErbB2-positive breast tumors have an activating mutation in p110α, a catalytic subunit of phosphoinositide 3-kinase (PI3K)." (PMID 28783168, 2017). "SPDEF belongs to the Ets family of transcription factors that is expressed in luminal, apocrine, and ErbB2-positive breast tumors and is associated with poor prognosis." (PMID 28915724, 2017). "If the correlation between ErbB2 mutations and drug responsiveness is confirmed in prospective clinical trials the screening for ErbB2 mutations in breast tumours will be mandatory before starting the therapy." (PMID 28417948, 2017). "With an intuitive search interface, it is thus possible to retrieve CGDs associated with ERBB2 amplification across cell lines from all tissue types or specifically associated with ERBB2 amplification in breast tumor models." (PMID 28711281, 2017). "HER2/ErbB2 is overexpressed in a significant fraction of breast tumours and is associated with a poor prognosis." (PMID 28912526, 2017). "On the other hand, another study showed elevated RUNX2 expression in all tumor subtypes, but its highest level was found in HER2/ErbB2 positive tumors and a significant poor prognosis was associated with the ER-negative subtype of breast tumor." (PMID 26404249, 2015). "Using RPPA analysis to detect changes in signal transduction pathways in primary breast tumors, we observed major shifts in cellular signaling specifically in primary LKB1-deficient ErbB2-positive breast tumors." (PMID 24280377, 2013). "In fact, ERBB2 gene amplification is found in 20−30% of primary breast tumors, and it is usually associated with poor clinical prognosis." (PMID 23421821, 2013).
breast tumors (continued). "To assess the impact of LKB1 loss on the metabolism of ErbB2-positive breast tumors, we conducted bioenergetic profiling of NIC tumor cells in vitro using an extracellular flux analyzer." (PMID 24280377, 2013). "One of the striking features observed in primary LKB1-deficient ErbB2-postive breast tumors is the amplification of signal transduction pathways impacting cell growth and metabolism." (PMID 24280377, 2013). "The human ERBB2 gene is frequently amplified in breast tumors, and its high expression is associated with poor prognosis." (PMID 23421821, 2013). "The luminal cluster predominantly harboring luminal breast tumors (ER/PR+, HER2+/−) was associated with strong overexpression of the estrogen receptor (ESR1) and the ERBB2 oncogene." (PMID 23049873, 2012). "SUMO-deficient (phospho-Ser294) PR gene signatures are significantly associated with human epidermal growth factor 2 (ERBB2)-positive luminal breast tumors and predictive of early metastasis and shortened survival." (PMID 22697792, 2012). "Recently, it was reported that MRK-003 GSI treatment of Balb/c-neuT female mice reduced tumour onset, tumour burden, and AKT1/mTOR activities associated with ErbB-2-positive, murine breast tumours." (PMID 21847123, 2011). "One recent study applied a standardised methodology used in breast tumour diagnostic assessment to measure both gene amplification and expression of ERBB2." (PMID 21364580, 2011). "ERBB2 expression constitutes a well known marker of breast tumors aggressiveness and its overexpression is associated with a worse prognostic and reduced survival." (PMID 20126619, 2010). "Specifically, HER2-enriched breast tumors (ERBB2+ and luminal B) were associated with the hypermethylation of several genes related to cancer development." (PMID 20920229, 2010). "It has been demonstrated that amplification of ERBB2 in BC cell lines and in primary breast tumors is associated with simultaneous amplification or deletion of the TOP2A gene." (PMID 18702822, 2008). "We hope that these data open a new way in the research field of ERBB2 overexpression and its pathogenic role in breast tumors." (PMID 18218085, 2008). "The ERBB2 gene is amplified and/or overexpressed in approximately 30% of breast tumours, a phenomenon that is associated with a poor prognosis." (PMID 17132159, 2006). "EGFR and ErbB2 co-overexpression in breast tumors is associated with resistance to endocrine therapies (and references therein)." (PMID 16371159, 2005). "In this review, we describe the prevalence of HER2-positive breast tumors by ethnicity, with a special focus on Asian and Latina women, along with genetic variants located in or near ERBB2 that might affect its protein expression." (PMID 40777119, 2025). "To investigate the underlying mechanism for ERBB2 promotion of autophagy, we examined the expression of several essential autophagy genes affected by ERBB2 expression in human breast tumor tissues via bioinformatics analysis of the data in the Oncomine database." (PMID 33801244, 2021). "The molecular features typically used for breast tumor subtyping include expression of the estrogen receptor (ER) and the progesterone receptor (PR), activation of human epidermal growth factor receptor 2 (HER2/neu, encoded by ERBB2), and/or the presence of BRCA1/2 mutations." (PMID 33352803, 2020). "Thus, Irf6 upregulation in patient-derived breast tumors is associated with ErbB2-targeted therapies." (PMID 30545388, 2018). "GATA3 is positively associated with ESR1, while TRPS1 is correlated with ERBB2 and might act as a potential modulator of chemosensitivity in breast tumor." (PMID 28423734, 2017). "Our results suggest that the expression of ERBB2, a crucial gene in breast cancer tumor subtype classification associated with poor prognosis, might be associated with genetic ancestry in breast tumor samples from Colombian women." (PMID 28832682, 2017).
breast tumors (continued). "In animal model, STAT1−/− may promote the spontaneous formation of breast tumors, with increasing susceptibility to tumorigensis initiated by ErbB2 and chemical carcinogenesis." (PMID 28422733, 2017). "However, in breast tumors, Ras is rarely mutated, but nonetheless it is continuously activated because of excessive stimulation of RTKs such as ErbB2." (PMID 24598028, 2014). "In addition, the results of statistical analysis show both amplification and LOH on 17q12 are significant, indicating only one of the two alleles for ERBB2 oncogene tends to be exclusively duplicated in these breast tumors." (PMID 24498045, 2014). "Thus, despite differences in tumor latency, both models indicate that LKB1 loss can cooperate with ErbB2 to promote breast tumor initiation." (PMID 24280377, 2013). "In this study, by combining the use of trapping heteroduplexes and RNA amplification, we developed a powerful approach that enables transcriptome-wide exploration of the AS repertoire for identifying AS variants associated with breast tumor cells modulated by ERBB2 (HER-2/neu) oncogene expression." (PMID 21210970, 2010). "In addition, enhanced levels of MMP2 in breast tumors are associated with ErbB2 gene amplification and/or overexpression." (PMID 20649976, 2010). "For example, GATA3 mutation predicts a better response to aromatase inhibition; PI3K or ERBB2 mutations may sensitize HER2 positive breast tumors to neoadjuvant chemotherapy (NACT) (docetaxel, carboplatin) in association with anti-HER2 treatment (trastuzumab, lapatinib)." (PMID 33906694, 2021). "Interestingly, ErbB4 is for instance associated with the acquired resistance to ErbB2-inhibitors in HER2+ breast tumors, probably via a shift in the dependency towards ErbB4 signaling following continuous ErbB2 blocking, though additional resistance mechanisms should account." (PMID 33912195, 2021). "In addition, we observed changes in the expression of specific genes, including significant reductions in the expression of Rb1, Esr1, and Pgr, and increases in the expression of Erbb2, Egfr, and the genes encoding keratins 5, 6, and 17, as they are in human basal-like breast tumors." (PMID 33652981, 2021). "Indeed, in SKBR3 breast tumor cells, it was recently shown that Memo controls the association of RhoA and its effector mDia with the plasma membrane in response to ErbB2 activation, thereby impacting on recruitment of actin-binding proteins, MT dynamics and migration." (PMID 22412880, 2012). "In contrast, ERBB2 amplification/HER2 overexpression is observed in approximately 20–30% of primary breast tumors." (PMID 41154672, 2025). "In HER2-positive breast tumors, palindromic DNA sequences are enriched near amplified oncogenes such as ERBB2." (PMID 41153425, 2025). "Of the six summits in the breast tumor sample, ERBB2 and MSL1 also appeared in the colon tumor sample, whereas no other samples showed prominent summits above normal in Chr17q12–21." (PMID 39946483, 2025). "Intriguingly, MCF7-TamC3 cells also exhibit characteristics that resemble the luminal B-ERBB2+ breast tumor subtype, like the increased expression of ERBB2 and the increased sensitivity to monoclonal ERBB2-targeting antibody Trastuzumab in vitro." (PMID 39991577, 2025). "This study aims to explore potential drug synergies by analyzing gene–drug interactions and combination therapies that target the ERBB2 pathway in HER2+ breast tumors." (PMID 39684551, 2024). "This study provides a comprehensive analysis of potential drug synergies through the ERBB2 pathway in HER2+ breast tumors, emphasizing the importance of combination therapies to enhance therapeutic efficacy." (PMID 39684551, 2024). "To study this possibility, we analyzed the expression of MERIT40 in 499 breast tumors (Curie cohort) classified into four subtypes according to their hormone receptors (ER/PR) and ERBB2 status." (PMID 37248434, 2023).
breast tumors (continued). "Since trastuzumab is representative of the standard treatment of HER-2 positive breast tumors, we studied its effect in combination with the PPRHs against the ERBB2 gene." (PMID 37108234, 2023). "published a meta-analysis of gene expression profiles with three gene modules (proliferation, ER signaling and ERBB2 amplification) in 2833 breast tumor to better understand cancer subtyping and prognosis signatures." (PMID 37313470, 2023). "By ISH, a breast tumor is considered HER2‐positive if the ratio of ERBB2 to chromosome enumeration probe 17 (CEP17) is ≥2.0 and the average ERBB2 copy number is ≥4.0." (PMID 37119523, 2023). "We describe the effect of two Polypurine Reverse Hoogsteen (PPRH) hairpins directed against the ERBB2 gene, which is overexpressed in positive HER-2 breast tumors." (PMID 37108234, 2023). "Subsequent preclinical studies have established the critical role of ERBB2ΔEx16 in the increased aggressiveness of HER2-positive breast tumors." (PMID 36686783, 2022). "HER2 protein overexpression and/or ERBB2 amplification are present in 15–20% of breast tumors and has been established as a predictive factor of prognosis." (PMID 36077795, 2022). "Studies in cell line and human breast tumors reported that BCAR4-mediated anti-estrogen therapy resistance is driven by HER2/ErbB2, ErbB3, and ErbB4 signaling." (PMID 36358625, 2022). "It has been also established that PTPN9 stimulated the dephosphorylation of EGFR and ErbB2 in breast tumor cells." (PMID 35156900, 2022). "Breast tumors characteristically show HER2/ERBB2 amplifications in the HER2 subgroup, chromosome (chr) 5q loss and chr10p amplifications in Basal-like BCs, chr 1q and chr 16q deletions in Luminal BCs." (PMID 36140723, 2022). "In summary, we discovered a novel mechanism of ErbB2-driven 3D breast tumor growth mediated by ErbB2-dependent BLNK downregulation." (PMID 35933456, 2022). "The receptor tyrosine kinase ERBB2 is overexpressed in 15–20% of breast tumors and increased ERBB2 is capable of enhancing cancer cell proliferation and invasion, which is associated with a poor prognosis for overall survival." (PMID 35431974, 2022). "In summary, we have discovered a novel mechanism of ErbB2-driven breast tumor growth driven by ErbB2-dependent BLNK downregulation." (PMID 35933456, 2022). "More particularly, HER2+ BC represents 15-20% of all breast tumors and is defined by the Erb-B2 receptor tyrosine kinase 2 (ERBB2)/HER2 gene amplification that leads to overexpression of the transmembrane tyrosine kinase receptor protein." (PMID 35371692, 2022). "In clinical practice, breast tumors are classified based on the histological expression of ERα, progesterone receptor (PR), receptor tyrosine-protein kinase ErbB-2 (HER2), and the proliferation marker Ki-67." (PMID 35052683, 2021). "Overexpression of the erbB-2 in breast tumors has been suggested to be a predictor of the therapeutic response to DOX." (PMID 34944912, 2021). "We further showed that ATG12 expression in breast tumors containing ERBB2 correlated with a worse patient survival outcome." (PMID 33801244, 2021). "Among breast tumors with amplified ERBB2 (the gene that expresses the HER2 receptor), 30% were also amplified for the MIR21 genomic region." (PMID 34797887, 2021). "All 19 non-breast tumors had ERBB2 amplification (estimated CN above 3.0) and varying HER2 IHC scores." (PMID 33710417, 2021).
breast tumors (continued). "HA–CD44 interactions have been shown to be involved in multidrug resistance in breast tumor cells and are linked to a positive feedback circuit involving HA, phosphoinositide 3-kinase (PI3K), and ErbB2." (PMID 33834020, 2021). "In this study, we trained a deep learning model with digital images of hematoxylin–eosin (H&E)-stained formalin-fixed primary breast tumor tissue sections, weakly supervised by ERBB2 gene amplification status." (PMID 33597560, 2021). "HER2/ERBB2-positive breast tumors receive intravenous medicine that specifically targets the HER2 protein, such as Trastuzumab, combined with chemotherapy." (PMID 33923160, 2021). "Another unmet need in the biomarkers of trastuzumab efficacy relates to the fact that ErbB2-positive breast tumors often metastasize to the bone." (PMID 33023655, 2020). "Herceptin and its derivatives have been used to treat breast tumors with amplified HER2 (or ERBB2) on 17q, but resistance to these therapies frequently develops in patients." (PMID 32408897, 2020). "Suppression of ErbB2 breast tumors by MEDICA is due to lipid raft disruption with loss of ErbB family members, including EGFR, ErbB2, and ErbB3." (PMID 32695336, 2020). "Transtuzumab (Herceptin®), a humanized version of mouse anti-ErbB-2 clone 4D5, is clinically used to treat metastatic breast tumors that overexpress HER2." (PMID 32075083, 2020). "Mitochondrial targeting by MEDICA suppresses ErbB2 breast tumors and metastasis due to lipid raft disruption and inhibition of mTORC1 activity." (PMID 32695336, 2020). "We found previously that ErbB2-driven downregulation of a pro-apoptotic protein PERP in breast tumor cells blocks their anoikis and that various ErbB2 antagonists upregulate PERP in these cells." (PMID 33023655, 2020). "MEDICA treatment is shown here to suppress ErbB2 breast tumors and lung metastasis in transgenic mice that express the activated ErbB2/neu oncogene under the control of the mouse MMTV long terminal repeat (LTR) promoter." (PMID 32695336, 2020). "Among the molecular markers employed in routine clinical practice for prognosis and predictive aims, human epidermal growth factor receptor 2 (HER2; ErbB2) defines a discrete category of breast tumors with specific characteristics." (PMID 32365528, 2020). "Supporting the importance of this phospho-site in vivo, serine 27 phosphorylation was found in an ErbB2-positive breast tumor sample in a proteomics study covering 105 breast tumors that were characterized for TCGA." (PMID 31963147, 2020). "Consistent with our published studies, p66ShcA increases Vimentin expression in ErbB2+ luminal breast tumors (NIC) whereas E-Cadherin levels are largely unaffected compared to control tumors." (PMID 31941526, 2020). "Amplified chromosomal regions are well known in breast tumors, particularly the amplifications of the ERBB2 locus at 17q12." (PMID 31442252, 2019). "In the particular case of HER2-positive breast tumors, gene profiling studies have shown that highly suspicious calcifications are associated with decreased immune system activity and ERBB2 overexpression." (PMID 31756919, 2019). "Overall, these findings indicate that c-Src ablation correlates with reduced PRC2 function in ErbB2-driven breast tumors." (PMID 31263101, 2019). "Our results suggest that treatment with a PRMT5 inhibitor in a syngeneic mouse erbB2/neu breast tumor model shows only a slight effect on tumor growth by itself, but significantly enhanced anti-erbB2 targeted antibody therapy." (PMID 30800128, 2019). "GATA3, ZNF703, and MAP3K1 are in the group 1 genes associated with acquired endocrine therapy resistance in breast tumors expressing ESR1 and ERBB2." (PMID 29738475, 2018).